HMGB1 (high mobility group box 1)
Diseases named in the same sentence as HMGB1 in open-access papers (continued):
Sharing a sentence is not in itself a finding about the gene and the disease.
Sepsis (continued). "Overall, we demonstrated that the disruption of neurotransmitters, impairment of neurongenesis and activation of astrocytes coupled with concomitant neuro-inflammation via HMGB-1/TLR4 signaling pathway were the potential pathogenesis of cognitive impairment in sepsis survivors." (PMID 28059131, 2017). "However, some studies have demonstrated that splenectomy protected against sepsis lethality and reduced serum HMGB1 levels, and splenectomy was detrimental to the immune response to lung infection." (PMID 28529765, 2017). "HMGB1 is secreted by macrophages in the later stages of sepsis through an unconventional pathway." (PMID 28067797, 2017). "Furthermore, we elucidated that salidroside prevented the HMGB1 nucleocytoplasmic translocation and HMGB1 release during sepsis via a SIRT1-mediated signaling pathway." (PMID 28931916, 2017). "Additionally, anti-HMGB1 treated murine sepsis survivors were significantly more resistant to secondary bacterial infection and exhibited altered innate immune cell phenotypes and cytokine responses." (PMID 28724977, 2017). "Our findings indicated that miR-181a-5p may play a role in regulating DC response to HMGB1 and serve as evidence supporting the idea that targeting miRNAs may represent a novel strategy for treating of immune dysfunction in the setting of sepsis." (PMID 28947753, 2017). "Ethyl pyruvate, the first HMGB1 inhibitor used in animal sepsis models to inhibit NF‐κB pathway, could inhibit tumour cell growth." (PMID 28039939, 2017). "When sepsis occurs, HMGB1, which regulates miR-181a expression, may also be regulated by miR-181a, and the two molecules may form a complex network to fine-tune cellular function and thus maintain immune homeostasis." (PMID 28947753, 2017). "Mice subjected to CLP-surgery had significantly higher serum HMGB1 than sham-surgery controls, though HMGB1 release was earlier and more transient than in patient groups, which may reflect the kinetics of sepsis induced by CLP." (PMID 28724977, 2017). "These pre-clinical data correlate with clinical studies showing that sepsis survivors have permanent cognitive deficits and that these may also be mediated via HMGB1, but the precise mechanism remains unknown." (PMID 27553758, 2016). "However, despite these interesting roles of HMGB-1 in the pathogenesis of various diseases, including sepsis, arthritis, ischemic injury, researchers are yet to study the involvement of HMGB-1 in endometriosis." (PMID 26872033, 2016). "In the present study, we investigated naringin’s mechanism of action and its inhibitory effect on lipopolysaccharide-induced tumor necrosis factor-alpha and high-mobility group box 1 expression in macrophages, and on death in a cecal ligation and puncture induced mouse model of sepsis." (PMID 27716835, 2016). "HMGB1 is a ubiquitous nuclear protein that can be actively secreted by immunocompetent cells, including monocytes, macrophages and neutrophils, and this highly conservative nuclear protein is an important late inflammatory mediator in sepsis." (PMID 27980458, 2016). "Active leakage (secretion) and passive leakage are known as mechanisms that increase plasma levels of HMGB-1, and these mechanisms may contribute differently to the pathophysiologies of sepsis and trauma." (PMID 27247778, 2016). "Although plasma levels of HMGB-1 and mtDNA on the day of admission were higher than those of the other days, which decrease gradually during the initial 7 days, in patients with severe trauma, plasma HMGB-1 and mtDNA were sustained in elevated levels in patients with sepsis." (PMID 27247778, 2016). "This would indicate that our model is beginning to accurately reflect biological situations since this parallels the in vivo experience where a persistent elevation of HMGB-1 in patients with severe sepsis and mice with organ damage have high HMGB-1 concentrations." (PMID 27556404, 2016).
Sepsis (continued). "TLR4 were mainly responded to PAMPs (such as LPS) and DAMPs (such as HMGB1), whose excessive activation could stimulate macrophages, DCs, and neutrophils which play a vital role in adaptive immunity by contributing to sepsis." (PMID 28082984, 2016). "HMGB1, as an endogenous danger signal triggering inflammatory responses, appears to play an important role in the pathogenesis of several inflammatory conditions, including sepsis, arthritis, cancer, and autoimmunity diseases." (PMID 28101517, 2016). "Delayed treatment with EP (40 mg/kg intraperitoneally injected 24 h, 30 h, 48 h, and 54 h after cecal puncture, the experiment finished 120 h after cecal puncture) significantly increases survival and markedly reduces circulating levels of HMGB1 in mice with sepsis." (PMID 27980458, 2016). "Furthermore, α2A-adrenoceptor blockade also improves sepsis-induced acute lung injury (ALI) accompanied by depressed levels of HMGB-1 in rats." (PMID 27347929, 2016). "High-mobility group box 1 has been recognized as a damage-associated molecular pattern (DAMP), and it has been implicated in several bacterial diseases, including inflammatory lung injury, pneumonia, sepsis, and keratitis." (PMID 27667993, 2016). "Recent experimental evidences indicate that EGCG can induce the aggregation of HMGB1 protein, a late mediator of inflammation, which subsequently stimulates the autophagic degradation and thus provides protection from lethal endotoxemia and sepsis." (PMID 26899177, 2016). "A number of studies have demonstrated that many promising agents are effective on controlling animal sepsis, including low doses of corticosteroids, LPS-target agents and blockers of inflammatory molecules, as well as anti-HMGB1 (high mobility group box 1) antibody and anti-IL-17A antibody." (PMID 27389701, 2016). "This likelihood is supported by recent findings that HMGB1 is persistently elevated during late-stage sepsis despite the cessation of initial infection and that it contributes to the long-term pathological consequence of sepsis." (PMID 26257917, 2015). "In CLP-treated septic mice, p38 MAPK inhibitor (SB203580) significantly inhibited high mobility group box 1 (HMGB-1) release and increased survival rate, HMGB-1 is an endogenous ligand for TLR4, in addition to LPS, and an important mediator of sepsis-associated death in experimental studies." (PMID 26063982, 2015). "In the current study, HMGB1 increased endothelial hyperpermeability, which was consistent with recent data suggesting that HMGB1 is involved in the pathophysiology of hyperpermeability of endothelial cell monolayers in sepsis." (PMID 25884983, 2015). "Moreover, HMGB1 release is observed in macrophages during phagocytic clearance of apoptotic cells in sepsis." (PMID 25904867, 2015). "Notably, agents capable of inhibiting HMGB1 release or action confer protection against sepsis, particularly if administered in a delayed fashion to strategically preserve the PAMPs-mediated early inflammatory response." (PMID 26257917, 2015). "HMGB1, a so-called endogenous danger signaling molecule, is actively released by activated monocytes and macrophages and is a key late mediator of the inflammatory response to sepsis, with levels corresponding to the onset of mortality." (PMID 26215802, 2015). "Indeed, HMGB1 is released into the extracellular milieu during sepsis and neutralization of this protein by monoclonal antibody treatment blocks sepsis development." (PMID 26441984, 2015). "Altogether, these studies suggest that extracellular HMGB1 is a proinflammatory signal to recruit, alert, and activate innate immune cells, thereby sustaining a potentially injurious inflammatory response during sepsis." (PMID 26257917, 2015). "Additionally, Salviae miltiorrhizae and Angelicae sinensis, which are two major components of the Xuebijing, have been proven to be protective against sepsis by inhibiting HMGB1 release." (PMID 25821501, 2015).
Sepsis (continued). "However, HMGB1 gained particular interest in the last decade after it was shown that it had a proinflammatory role in endotoxin lethality in mice and in sepsis after its release from damaged or necrotic cells." (PMID 24804269, 2014). "Extracellular HMGB1 up-regulates inflammatory response in sepsis as a late mediator." (PMID 24924349, 2014). "Importantly, the knock-down of caspase-1 gene reduced splenic cell death in an E. coli induced-sepsis model and HMGB-1 release in an LPS induced-endotoxemia model, and improved the survival rates in both models." (PMID 24454930, 2014). "Therefore, preventing the active release and inhibiting the pro-inflammatory activity of HMGB1 become promising strategies for the treatment of sepsis." (PMID 24603876, 2014). "Furthermore, the levels of HMGB1 were the highest in the subgroup of sJIA patients with hepatosplenomegaly or serositis, which is in accordance with the known release of HMGB1 in acute systemic inflammatory conditions such as sepsis." (PMID 25516724, 2014). "During sepsis, HMGB1 could be rapidly and passively released upon cell death due to infection and also could be actively secreted by immune cells in response to pro-inflammatory cytokines and pathogen-associated molecular patterns (PAMPs)." (PMID 24603876, 2014). "HMGB1 has been proven to be a successful therapeutic target for the treatment of sepsis." (PMID 24603876, 2014). "HMGB1 was reported as a late responding signal molecule in sepsis." (PMID 24924349, 2014). "Therefore, in this study, we investigated the relationship between Gu-4 and HMGB1, a critical late mediator in endotoxemia and sepsis, and we found that Gu-4 inhibited the active release and the pro-inflammatory activity of HMGB1." (PMID 24603876, 2014). "The cytokine HMGB1 is involved in sepsis-induced myocyte apoptosis." (PMID 25210949, 2014). "Circulating HMGB1 levels are elevated in many inflammatory disease conditions including sepsis.To test whether DNA beads capture and remove HMGB1 in the serum, we utilized an established model of murine sepsis induced by cecal ligation and puncture (CLP)." (PMID 25127031, 2014). "The CS model had the greatest gene expression related to innate inflammatory pathways one day after sepsis with activation of pathways related to the role of pattern recognition receptors (PRRs), Il-1, Il-6, Nfkb, and Hmgb1 signaling, chemokine signing, TLR signaling, and the acute phase response." (PMID 24788351, 2014). "If so, HMGB1-based strategies might represent a novel therapeutic approach for severe P. falciparum infection, as proposed for sepsis." (PMID 23506269, 2013). "Further Cbl/sepsis studies should include measurement of plasma HMGB1 levels." (PMID 23781123, 2013). "Moreover, increased levels of HMGB1 are observed in patients with sepsis and other major inflammatory diseases, including rheumatoid arthritis." (PMID 23737912, 2013). "Our observation that C23–45 HMGB1 stimulates splenocytes to produce more TNF in response to endotoxin ex vivo suggests that serum HMGB1 elevation in murine sepsis survivors can contribute to the observed monocyte population shift towards the Ly-6Chigh TNF production-prone phenotype." (PMID 23808943, 2013). "In addition to its nuclear expression, HMGB1 can be released from inflammatory cells and necrotic tissues during endotoxemia and sepsis." (PMID 24371375, 2013). "Serum high-mobility group box 1 (HMGB1) levels in the sepsis surviving mice were significantly elevated for 4-6 weeks after post-sepsis, and administration of an anti-HMGB1 monoclonal antibody significantly attenuated splenomegaly as well as splenocyte priming." (PMID 23808943, 2013). "HMGB1 levels are markedly increased during severe sepsis in humans and mice." (PMID 24065095, 2013). "Taken together, PlGF, PAPP-A, sRAGE, EN-RAGE and HMGB-1 might play a role also in sepsis induced AKI." (PMID 24188108, 2013). "HMGB-1 was persistently elevated in patients with severe sepsis and severe shock." (PMID 24188108, 2013).
Sepsis (continued). "HMGB1 has previously been reported to be a cytokine that mediates organ damage in severe sepsis." (PMID 24371375, 2013). "The findings of the present study indicate that the pathophysiology of this phenomenon in sepsis survivors may be dependent upon HMGB1." (PMID 23808943, 2013). "During the course of investigating this novel murine model of sepsis survivors, we unexpectedly observed significant splenomegaly in a time period that seemed to correlate with the appearance of delayed increases in serum HMGB1 levels." (PMID 23808943, 2013). "In addition, the HMGB1 level is higher in HO-1−/− mice than in HO-1+/+ mice when animals are subjected to either LPS injection or CLP-induced polymicrobial sepsis, indicating that HO-1 negatively regulates HMGB1 under septic conditions." (PMID 24098466, 2013). "However, the mechanisms of ATF3 and the role of HMGB1 in regulating innate immunity-induced sepsis are incompletely understood." (PMID 24062788, 2013). "In addition to its function in sepsis, the activity of HMGB1 in I/R injury has also been explored by scientists worldwide." (PMID 24453420, 2013). "Sodium butyrate, an inhibitor of histone deacetylase, has been reported that it could provide an anti-inflammatory effect and could inhibit HMGB1 expression in sepsis, ischemic stroke, myocardial ischemia/reperfusion, and lipopolysaccharide (LPS)-induced ALI." (PMID 23874764, 2013). "Inhibition of inflammation and blockade of HMGB1-TLR 4 vicious circle by ATF3 during endotoxemia may prevent patients from sepsis-mediated mortality." (PMID 24062788, 2013). "Furthermore, glucan phosphate, a carbohydrate ligand that modulates innate immunity and proinflammatory signaling in sepsis, has been shown to improve cardiac function and HMGB1 translocation from the nucleus to the cytoplasm in the myocardium." (PMID 23532259, 2013). "Total serum HMGB1 levels, measured by quantitative immunoblotting, were significantly elevated for at least 8 weeks in severe sepsis survivors and returned to baseline levels within 12 weeks; this kinetic pattern correlates closely with the onset of splenomegaly." (PMID 23808943, 2013). "Since ATF3 modulates the secretion and release of HMGB1, which is a down-stream proinflammatory mediator and may more closely reflect the status of sepsis, we, therefore, examined its level in sepsis patients." (PMID 24062788, 2013). "The effect of HMGB1 on vascular reactivity during sepsis remains to be clarified." (PMID 23532259, 2013). "Not only TNF-α but also HMGB1 plays a crucial role in lethality during sepsis." (PMID 24098466, 2013). "The harmful substances such as DNA, histones, and high-mobility group box 1 (HMGB1) and many other danger-associated molecular patterns (DAMPs) released along with NETosis or from necrotic neutrophils also contribute to the pathogenesis of sepsis." (PMID 25705405, 2013). "On the other hand, high mobility group box 1 (HMGB1) is thought to be a late mediator of endotoxin lethality in mice, and HMGB1 is first detectable in the circulation 8 hours after the onset of sepsis disease, subsequently increasing to plateau levels from 16 to 32 hours." (PMID 24321251, 2013). "In addition, in patients with sepsis and after hemorrhage, the elevated level of HMGB-1 in their circulation is highly correlated with the occurrence of ALI." (PMID 23691208, 2013). "Protective effects of activated protein C in severe sepsis may partially be mediated through the inhibition of HMGB1 signaling." (PMID 24062788, 2013). "By reducing the serum level and gene expression of HMGB1 and other pro-inflammatory cytokines, GL may become a potential agent for the treatment of sepsis." (PMID 23497622, 2013). "Thus, accumulation of C23–45 HMGB1, which has been shown previously to be pro-inflammatory, occurs during the onset of splenomegaly in severe sepsis survivors." (PMID 23808943, 2013).
Sepsis (continued). "It has been recently found that dexmedetomidine reduces systemic levels of interleukin- 6 (IL-6), tumor necrosis factor α (TNF-α) and high mobility group box 1 (HMGB1) following lipopolysaccharide infusion or sepsis in animals, indicating its anti-inflammatory effects against renal I/R injury." (PMID 23759023, 2013). "HMGB1 has been identified as a lethal mediator of severe sepsis." (PMID 24065095, 2013). "Thus, future research should establish HMGB1 as a promising target for treatment of cardiac hypertrophy in diseases such as endotoxemia, sepsis, hemorrhagic shock, rheumatoid arthritis, type 2 diabetes, hypertension, and ST-elevation myocardial infarction." (PMID 22778498, 2012). "Antibody-induced neutralization or use of recombinant A box domain of HMGB1 (antagonist of B box proinflammatory activity) in sepsis could improve the outcome, even when applied after the onset of disease." (PMID 22778496, 2012). "There were no statistically different RAGE, sRAGE and HMGB-1 levels found during early CAP-associated sepsis in ARDS or non-surviving patients." (PMID 22264245, 2012). "However, other studies have shown that HMGB1 production occurred downstream of apoptosis in the final common pathway to organ damage in severe sepsis." (PMID 22277256, 2012). "HMGB-1 is a late mediator of septic sequelae that is released from the nucleus into the cytosol and systemic circulation in response to various stimuli including sepsis." (PMID 23028587, 2012). "In addition, it has recently been demonstrated that HMGB1 is an important late-phase mediator in the pathogenesis of sepsis." (PMID 22283426, 2012). "Moreover, an autophagy-related pathway emerges as a critical component in neutrophil function during sepsis by regulating the translocation of certain neutrophil proteins to NETs, including TF and HMGB1." (PMID 23029002, 2012). "HMGB1, a 25 KDa nuclear protein, is a late cytokine mediator of lethal endotoxemia and sepsis." (PMID 23209806, 2012). "Proinflammatory properties of HMGB1 as a crucial cytokine were first documented in a report demonstrating that HMGB1 is actively secreted by activated macrophages, serving as a late mediator of lethality in a mouse model of sepsis." (PMID 23316104, 2012). "Here, we demonstrate that PPARs are involved in the regulation of LPS-induced HMGB1 release in RAW 264.7 cells, and the administration of rosiglitazone, a specific ligand for PPARγ, attenuated endotoxin lethality by inhibiting HMGB1 release in a mouse model of sepsis." (PMID 23316104, 2012). "Interestingly HMGB1 serum levels are elevated in sepsis, and an experimental sepsis model with specific inhibition of HMGB1 activity demonstrated an improvement in the clinical course and survival rate." (PMID 22973073, 2012). "Furthermore, circulating HMGB1 levels were elevated with delayed fashion in the mouse model and in patients with sepsis characterized by overwhelming inflammatory and immune responses, leading to tissue damage, multiple-organ failure and death." (PMID 23316104, 2012). "Furthermore, HMGB1-neutralizing antibodies confer protection against lethal endotoxemia and sepsis even when given 24 h after the onset of sepsis, suggesting HMGB1 as a critically important late mediator of lethal sepsis." (PMID 23193422, 2012). "Thus, secreted HMGB1 also functions as an inflammatory cytokine, and its secretion is pivotal in sepsis." (PMID 21887276, 2011). "Indeed, it has been demonstrated that HMGB1 acts as a late mediator of sepsis and endotoxin lethality, is increased in the plasma of septic patients and its blockade improves survival of septic rodents 34–38." (PMID 21630250, 2011). "Administration of fetuin-A significantly reduced endotoxemia- or sepsis-induced increase of circulating HMGB1 levels at 52 h post endotoxemia or sepsis, suggesting that fetuin-A confers protection by inhibiting systemic accumulation of late proinflammatory mediator of these diseases." (PMID 21347455, 2011).